RANBP2 (RAN binding protein 2)
Diseases named in the same sentence as RANBP2 in open-access papers (continued):
Sharing a sentence is not in itself a finding about the gene and the disease.
HIV-1 infection (9 papers, 2010 to 2025). The type species of lentivirus and the etiologic agent of acquired immunodeficiency syndrome (AIDS). "Notably, various activities of Ranbp2 are also implicated in the modulation of HIV-1 infection." (PMID 28100513, 2017). "Sensitivity of HIV-1 to MX2 activity is affected by complex interactions between CA and cellular proteins involved in the early stages of HIV-1 infection (reviewed in reference 39), including RANBP2." (PMID 39853118, 2025). "Using this approach, we investigated the function of the Cyp homology domain of the cytoplasmic filament Nup RANBP2 in HIV-1 infection and MX2 activity." (PMID 39853118, 2025). "We have used precise gene editing to assess the role of the cyclophilin domain of RANBP2 in HIV-1 infection and MX2 activity." (PMID 39853118, 2025). "The effects of NUP153 depletion on HIV-1 infection in CsA treated cells were also similar to the effects of RANBP2 depletion, rendering HIV-1WT infection CsA dependent (as previously reported) and exaggerating the CsA dependence of HIV-1A94E in HeLa cells." (PMID 30084827, 2018). "In our investigations, we found that RanBP2 depletion via RNAi resulted in profound inhibition of HIV-1 infection and played a pivotal role in the nuclear entry of HIV DNA." (PMID 21179483, 2010). "In this study, we investigated the role of RanBP2 and found that it is an essential host factor for HIV-1 infection and is involved in promoting the nuclear import of HIV-1 DNA." (PMID 21179483, 2010). "To examine the potential role of CA-independent effects of RANBP2-Cyp on HIV-1 infection and MX2 activity, we next generated cells expressing RANBP2 from its endogenous locus but with specific point mutations introduced into the Cyp domain to alter CA-binding specificity." (PMID 39853118, 2025). "Although RanBP2 plays a critical role in the HIV-1 life cycle, it remains unclear whether HIV-1 infection could trigger ANE1." (PMID 35408907, 2022). "Therefore, it is possible that Daxx and RanBP2 interact independently of HIV-1 infection, possibly through the C-terminal cyclophilin domain of RanBP2." (PMID 32545337, 2020). "Put another way, CsA rescued WT HIV-1 infection of HeLa cells when RANBP2 or NUP153 were depleted." (PMID 30084827, 2018). "HIV-1 infection was impaired by Nup358/RanBP2, Nup153, or Nup160 knockdown." (PMID 22928108, 2012). "However, the precise role of the RANBP2-Cyp domain in HIV-1 infection remains controversial." (PMID 39853118, 2025). "Although RANBP2/NUP358 has been repeatedly identified as a critical player in HIV-1 nuclear import and MX2 activity, the mechanism by which RANBP2 facilitates HIV-1 infection is not well understood." (PMID 39853118, 2025). "There are different Nups and nuclear factors that have the ability to bind to HIV-1 cores and to participate in the early steps of HIV-1 infection: TNPO3, CPSF6, Nup358/RanBP2, Nup98, Nup214 and Nup153." (PMID 31569640, 2019). "While RANBP2 has previously been reported to enhance HIV-1 infection, the domains required and the mechanism by which RANBP2 facilitates HIV-1 infection remain controversial (reviewed in." (PMID 30084827, 2018). "The exception to this general finding was that CsA dramatically reduced the deleterious effects of RANBP2 and NUP153 depletion on WT HIV-1 infection of HeLa cells." (PMID 30084827, 2018). "One of the Nups, Nup358 (also known as RanBP2 or RAN binding protein 2), is a cellular co-factor for the HIV-1 infection at the PIC nuclear import step." (PMID 23087682, 2012). "Notably, the widely reported effects of RANBP2 and NUP153 on HIV-1 infection of HeLa cells were less evident in HT1080 cells." (PMID 30084827, 2018). "Like RANBP2, NUP153 has been reported to specifically enhance HIV-1 infection." (PMID 30084827, 2018).
HIV-1 infection (continued). "In summary, this report demonstrates a specific role for the Cyp domain of RANBP2 in HIV infection and MX2 sensitivity and further indicates that precise manipulation of NPCs is key to revealing the functional interactions that determine the outcome of HIV-1 infection." (PMID 39853118, 2025). "Interestingly, CsA treatment also rescues HIV-1 infection from RANBP2 (and NUP153) knockdown in some cell types, suggesting that CA interactions with both CypA and the RANBP2-Cyp domain determine the requirement for RANBP2." (PMID 39853118, 2025). "RANBP2 depletion changed some, but not all, of the effects of CypA on HIV-1 infection." (PMID 30084827, 2018).
Encephalopathy (7 papers, 2012 to 2024). Encephalopathy is a term that means brain disease, damage, or malfunction. "Familial ANE is a rapidly progressive encephalopathy associated a RANBP2 gene mutation." (PMID 33777149, 2021). "RYR3, known for its role in calcium signaling and synaptic plasticity, and RANBP2, associated with nuclear transport and encephalopathy, may converge in their impact on neural function via shared pathways, such as calcium homeostasis, neuronal signaling, or stress response pathways." (PMID 39509559, 2024). "Additionally, genetic risk factors are also suspected, such as RANBP2 in ANE and MYRF in mild encephalitis/encephalopathy with reversible splenial lesion (MERS)." (PMID 38528535, 2024).
acute necrotizing encephalopathy type 1 (5 papers, 2021 to 2025). "This subset of ANE patients with RanBP2 gene mutations is categorized as acute necrotizing encephalopathy type 1 (ANE1)." (PMID 40291183, 2025). "ANE associated with a RANBP2 mutation is subtyped as ANE1, also referred to as infection-induced acute encephalopathy 3 (IIAE3)." (PMID 40868426, 2025). "Since then, ANE associated with RanBP2 mutations has been termed ANE1, which has also been renamed as infection-induced acute encephalopathy 3 (IIAE3) in the Online Mendelian Inheritance in the Man (OMIM) repository." (PMID 35408907, 2022). "Loss-of-function variants in RANBP2 are associated with the autosomal dominant post-infectious and often fatal complication acute necrotizing encephalopathy type 1 (ANE1, MIM: 608033)." (PMID 35126383, 2021). "Acute necrotizing encephalopathy type 1 (ANE1) is recurrent, and familial cases have been associated with mutations in the RAN-binding protein 2 (RanBP2) gene." (PMID 40291183, 2025).
encephalitis (5 papers, 2012 to 2025). An acute inflammatory process affecting the brain parenchyma. "Mutation in the gene Ran-binding 2 (RANBP2) have been shown to be associated with familial or recurrent influenza-associated acute encephalopathy/encephalitis." (PMID 24744626, 2012).
inflammatory myofibroblastic tumor (5 papers, 2013 to 2020). A multinodular intermediate fibroblastic neoplasm that arises from soft tissue or viscera, in children and young adults. "Inflammatory myofibroblastic tumor with RANBP2 and ALK gene rearrangement." (PMID 32847129, 2020). "Inflammatory myofibroblastic tumors (IMTs) are categorized as intermediate biologic neoplasms, whereas IMTs with genetic features of ran-binding protein 2 (RANBP2) and anaplastic lymphoma kinase (ALK) rearrangement (IMT-RAs) are possibly related to a more aggressive clinical course." (PMID 24034896, 2013). "Among them, huntingdon-interacting protein (HIP1)-ALK and RAN-binding protein 2 (RANBP2)-ALK, which have been reported to exist in NSCLC and inflammatory myofibroblastic tumors, respectively, show clinical responses to crizotinib." (PMID 26295973, 2015). "Many translocations have been found with this ALK gene, including EML4:ALK which is responsible for approximately 3-5% of non-small-cell lung cancer(NSCLC), RANBP2:ALK, TPM4:ALK in inflammatory myofibroblastic tumor, NPM1:ALK, ATIC:ALK, TFG:ALK in anaplastic large cell lymphoma, and so on." (PMID 24564548, 2013).
prostate carcinoma (5 papers, 2020 to 2025). A carcinoma that arises from epithelial cells of the prostate gland. "In a search for G3BP2-interacting proteins in prostate cancer LNCaP cells, RanBP2 and TRIM25 were among the top interacting factors." (PMID 39851496, 2025).
colorectal cancer (4 papers, 2012 to 2025). A primary or metastatic malignant neoplasm that affects the colon or rectum. "In the discovery phase, we benefited from the highest quality data and identified that RANBP2 knockdown can kill the BRAF-mutation-like subtype of colorectal cancer cells." (PMID 29479053, 2017). "In BRAF-like colorectal cancer cells, the suppression of RANBP2-induced cell death is propelled by mitotic defects." (PMID 40271196, 2025). "In summary, RANBP2 mediates apoptosis in BRAF-like colorectal cancer cells by spindling apparatus movement during mitosis." (PMID 40271196, 2025). "For example, RANBP2, a binding protein of RAN (RAS related nuclear protein), a small GTPase of the RAS family, has been proposed as essential for survival of BRAF V600E mutant colorectal cancer cells and cells with a similar genomic signature." (PMID 36295658, 2022).
hepatocellular carcinoma (4 papers, 2021 to 2025). A malignant tumor that arises from hepatocytes. "Besides, SIRT1 activated RANBP2, indispensable for FTO SUMOylation at Lysine (K)−216 site, to enhance FTO degradation, leading to progression of hepatocellular carcinoma." (PMID 35945194, 2022).
influenza (4 papers, 2021 to 2025). An acute viral infection of the respiratory tract, occurring in isolated cases, in epidemics, or in pandemics; it is caused by serologically different strains of viruses (influenzaviruses) designated A, B, and C, has a 3-day incubation period, and usually lasts for 3 to 10 days. "A study including cases of RANBP2-mutation- and/or influenza-associated acute necrotising encephalopathy, however, did not reveal significant differences in MRI findings for positive versus negative RANBP2 status, with the small study cohort of 20 patients limiting the observation’s validity." (PMID 40868426, 2025). "Similarly, Ran Binding Protein 2 (RANBP2) mutation has been associated with fulminant necrotizing encephalitis of influenza, in which early prophylactic use of Tamiflu may prevent complication and fatality." (PMID 34335596, 2021). "Influenza-associated ANE is more prevalent in Asian countries than that in Western countries, but fewer cases were associated with RanBP2 mutation." (PMID 36430629, 2022). "The RANBP2 gene mutations increase the susceptibility to recurrent episodes of ANE with respiratory viral infections, particularly influenza infection." (PMID 36430629, 2022). "In addition to RanBP2 mutations, HLA, CPT2, SCN1A, and SLC19A3 mutations have been associated with influenza or COVID-19-associated ANE." (PMID 36430629, 2022). "Ran Binding Protein 2 (RANBP2) gene mutations increase the susceptibility to recurrent episodes of necrotizing encephalitis with respiratory viral infections, particularly influenza infection." (PMID 34335596, 2021).
lung carcinoma (4 papers, 2018 to 2024). "RanBP2 was identified as a new tumor suppressor in lung cancer and has been shown to play an essential role in cellular processes and protein stabilization, including the RAN protein." (PMID 39338204, 2024). "Consistently, two independent studies also demonstrated that RanBP2 level was downregulated in human lung cancers." (PMID 29706609, 2018).
Parkinson (4 papers, 2006 to 2025). "The marked increase in the steady state level of RANBP2 suggests a potential mechanism by which CA3 may enhance SUMOylation and nuclear transport, thereby stabilizing proteins implicated in neurodegenerative disorders such as Parkinson’s, Alzheimer’s, and Huntington’s diseases." (PMID 41465490, 2025). "MPTP led to stronger akinetic parkinsonism and slower recovery in Ranbp2+/− than wild-type mice without viability changes of brain TH+-neurons of either genotype, with the exception of transient nuclear atypia via changes in chromatin condensation of Ranbp2+/− TH+-neurons." (PMID 22821000, 2012).
breast carcinoma (3 papers, 2019 to 2025). "Other members of the nucleoporin family have been linked with cancer including Tpr, NUP62, NUP214 and NUP358/RanBP2 with NUP88 and more recently, NUP43 specifically linked to poor outcome in breast cancer." (PMID 30935371, 2019). "We identified components of a cytonuclear transport system, including importins KPNA2 and KPNB1, as well as a subunit of the NPC RANBP2, as binding partners of ARID1B in breast cancer cells." (PMID 40671262, 2025). "In conclusion, our study highlights alterations inthe methylation patterns of RANBP2, LCP2, andGRAP2 genes in breast cancer tissue, aligning withconsistent changes in methylation levels in bloodcfDNA." (PMID 39139156, 2024).
colon cancer (3 papers, 2021 to 2023). "A subset of colon cancers was reported to overexpress RANBP2, which modulated sensitivity to certain anti-microtubule drugs." (PMID 37947624, 2023). "The results obtained from HCT116 and DLD1 colon cancer cells paralleled those from USP9x siRNA knockdown in HEK293 parental cells, in which pIIIa and RANBP2 expression was significantly increased." (PMID 35709296, 2022).
COVID-19 (3 papers, 2021 to 2022). A disease caused by infection with severe acute respiratory syndrome coronavirus 2. "Role of RANBP2 mutation and its application in COVID-19 and ANE should be further elaborated." (PMID 35870896, 2022). "Here, we report a recently immunized patient (BBIBP-CorV–inactivated vaccine) with coronavirus disease-2019 (COVID-19) and ANE, who had extremely high interleukin-6 (IL-6) level and Ran Binding Protein 2 (RANBP2) missense mutation (The first case in COVID-19)." (PMID 35870896, 2022). "Second, several case studies indicated that COVID-19 can also lead to ANE-like cytokine storms in the brain; however, whether these patients bear mutations in RanBP2 or whether ANE1 mutations affect the response to SARS-CoV2 infection remains to be determined." (PMID 35408907, 2022). "We proposed these potential two factors (RANBP2 mutation and ADE) that could participate in the pathogenesis of ANE in COVID-19 apart from SARS-CoV2 infection by itself." (PMID 35870896, 2022). "We report the first case of COVID-19 associated acute necrotizing encephalopathy (ANE) without pulmonary disease in a patient with an extremely high interleukin-6 (IL-6) level and Ran Binding Protein 2 (RANBP2) mutation." (PMID 35870896, 2022).
neuroblastoma (3 papers, 2018 to 2025). Neuroblastoma (NB) is the most common solid, extracranial childhood tumor. "Other environmental factors, such as dietary habit, childhood exposure, and health situation, would help to provide further insight into the influence of RAN/RANBP2 polymorphisms on neuroblastoma risk." (PMID 29706609, 2018). "The current study was the first investigation on the association of RAN/RANBP2 genes SNPs with neuroblastoma risk." (PMID 29706609, 2018). "In all, here we demonstrate that common variants at the RAN/RANBP2 genes are associated with the risk of neuroblastoma in the Chinese children in a low-impact manner." (PMID 29706609, 2018). "In the current study, we performed the first investigation into the impact of SNPs in RAN/RANBP2 genes on the risk of neuroblastoma in Chinese Han children." (PMID 29706609, 2018). "Further studies are warranted to validate the weak impact of RAN/RANBP2 SNPs on neuroblastoma risk." (PMID 29706609, 2018). "Given the unknown role of RAN/RANBP2 single nucleotide polymorphisms (SNPs) in neuroblastoma risk, we performed a multi-center case-control study in Chinese children to assess the association of the RAN/RANBP2 SNPs with neuroblastoma risk." (PMID 29706609, 2018). "Association of RAN and RANBP2 polymorphisms with neuroblastoma risk." (PMID 29706609, 2018). "Herein, for the first time we investigated whether RAN/RANBP2 SNPs could contribute to the risk of neuroblastoma in Chinese children." (PMID 29706609, 2018). "However, the association of polymorphisms in the RAN/RANBP2 genes and neuroblastoma risk has yet to be elucidated." (PMID 29706609, 2018). "Future larger-sample, functional studies are warranted to address the mechanism by which RAN/RANBP2 SNPs impacts tumorigenesis of neuroblastoma." (PMID 29706609, 2018). "Our data revealed that the single RAN or RANBP2 gene polymorphism might not be strong enough to confer the neuroblastoma susceptibility in Chinese children." (PMID 29706609, 2018). "LIN28B cooperates with RANBP2 to promote RAN expression and activity of RAN GTPase, thereby driving the oncogenesis of neuroblastoma." (PMID 33816306, 2021).
adenovirus infection (2 papers, 2022). "We suggest a model for adenovirus infection in which USP9x acts indirectly to negatively regulate pIIIa-RANBP2 interactions." (PMID 35709296, 2022).
cholangiocarcinoma (2 papers, 2017 to 2025). A carcinoma that arises from the intrahepatic biliary tree (intrahepatic cholangiocarcinoma) or from the junction, or adjacent to the junction, of the right and left hepatic ducts (hilar cholangiocarcinoma). "Considering our study in the cholangiocarcinoma, together with all the publications concerning RanBP2 and sumoylation, the role of RanBP2 is more likely dependent on its target protein." (PMID 28882106, 2017).
epilepsy (2 papers, 2024 to 2025). A brain disorder characterized by episodes of abnormally increased neuronal discharge resulting in transient episodes of sensory or motor neurological dysfunction, or psychic dysfunction. "Identifying specific pathogenic variants in genes such as SCN1A, SCN9A, and QARS1 and the recurrent combination of RANBP2 and RYR3 variants underscores the necessity for ongoing research to elucidate their roles in epilepsy development." (PMID 39509559, 2024). "Following analyzing the detected variants from unaffected biological parents' tests, it was observed that one RYR3 & Ranbp2 combination was inherited, with each variant originating from a different parent, suggesting that the combination of genes may be the cause of the child's epilepsy." (PMID 39509559, 2024). "Identifying potentially pathogenic variants like those found in SCN9A and QARS1, as well as frequently co‐occurring combinations like RYR3 and RANBP2, offers valuable insights into the genetic foundations of epilepsy." (PMID 39509559, 2024). "Identification of potentially pathogenic variants and frequent genetic combinations, such as RANBP2&RYR3, could aid in understanding the genetic basis of epilepsy and identifying potential hotspots." (PMID 39509559, 2024). "Interestingly, the RANBP2 variants, when present as VUS, consistently co‐occurred with a variant of RYR3, suggesting a potential pathogenic role for this combination in contributing to the manifestation of epilepsy." (PMID 39509559, 2024). "This panel list of genes consists of preliminary evidence genes for epilepsy, Glycine Encephalopathy, FLNA, PTEN, and RANBP2 genes as well as Rett and ADs and related disorders." (PMID 39976384, 2025).
glioblastoma (2 papers, 2021 to 2025). The most malignant astrocytic tumor (WHO grade IV). "As can be seen from the figure, UBE2I, UBA2, PIAS3, and SENP1 were upregulated in glioblastoma, whereas PIAS1, RANBP2, SENP5, and SENP2 were downregulated in glioblastoma." (PMID 33898460, 2021). "PIAS1, RANBP2, SENP5, and SENP2 were downregulated in glioblastoma." (PMID 33898460, 2021). "Moreover, UBE2I, UBA2, PIAS3, and SENP1 were highly expressed in glioblastoma, whereas PIAS1, RANBP2, SENP5, and SENP2 were downregulated in glioblastoma." (PMID 33898460, 2021).